TBX3 (T-box transcription factor 3)
Diseases named in the same sentence as TBX3 in open-access papers (continued):
Sharing a sentence is not in itself a finding about the gene and the disease.
pancreatic ductal adenocarcinoma (1 paper, 2021). An infiltrating adenocarcinoma that arises from the epithelial cells of the pancreas. "Cancer stem cells (CSCs) comprise a subpopulation of cancer cells that drive tumor initiation and progression and TBX3 was reported to contribute to the expansion of breast CSCs and cancer stemness of ovarian and pancreatic ductal adenocarcinoma CSCs." (PMID 35145908, 2021). "Furthermore, the HOTAIR/miR‐206/TBX3 axis was shown to mediate cancer stemness of ovarian CSCs and pancreatic ductal adenocarcinoma CSCs express high levels of TBX3 and sustain stemness via an autocrine TBX3-ACTIVIN/NODAL signaling loop." (PMID 35145908, 2021).
pancreatitis (1 paper, 2023). Inflammation of the pancreas. "However, loss of Tbx3 leads to overshoot proliferation of acinar cells, accumulation of fibrosis, and enhanced inflammatory stimuli, Il6-Jak-Stat3, and acinar cell-specific NF-κB signaling during pancreatitis." (PMID 36941669, 2023). "Interestingly, gene expression analysis of Acta2 at 72h after the onset of pancreatitis confirmed the significant difference between Tbx3-KO (epi) and control mice." (PMID 36941669, 2023). "However, validation on protein level could only confirm an increased abundance of B cells in Tbx3-KO (epi) pancreata as compared to control (epi) counterparts at 72h after induction of pancreatitis." (PMID 36941669, 2023).
prurigo nodularis (1 paper, 2024). Prurigonodularis (PN) is a skin disease in which hard crusty lumps are formed on the skin that itches intensely. "Interestingly, a closer inspection of single-cell profiles identified some differences between prurigo nodularis and psoriasis lesions, with WNT5A+/IL24+ fibroblasts expressing TBX3 and CXCL8 only in the latter." (PMID 38291032, 2024).
resistant hypertension (1 paper, 2017). "The most significant finding in the present study was TBX3 rs35444, previously associated with increased diastolic blood pressure in East Asians, associated with resistant hypertension (eMERGE I and II combined odds ratio = 1.27; p = 1.30x10-3) in this multi-ethnic clinical study." (PMID 28222112, 2017).
rheumatoid arthritis (1 paper, 2019). A chronic, systemic autoimmune disorder characterized by inflammation in the synovial membranes and articular surfaces. "We also propose TBX3 as a putative diagnostic biomarker for rheumatoid arthritis." (PMID 30630509, 2019).
sleep abnormalities (1 paper, 2015). "And function of tbx3 in neurons may be effective in populations with sleep abnormalities." (PMID 26722632, 2015).
squamous cell carcinoma (1 paper, 2024). A carcinoma arising from squamous epithelial cells. "Like TBX2, TBX3 has decreased protein expression by 1.5-fold in pulmonary adenocarcinoma, and by onefold in non-squamous cell carcinoma." (PMID 38413457, 2024).
thyroid tumor (1 paper, 2024). A benign or malignant neoplasm affecting the thyroid gland. "Here, the authors show that MAPK activation upregulates USP15 to promote deubiquitylation and stability of TBX3, a transcription factor implicated in thyroid development and differentiation, driving tumorigenesis in a BRAFV600E thyroid tumor model." (PMID 38750011, 2024). "Tbx3 and Usp15 deficiency both lead to differentiation augmentation, exemplified with excessive Tpo, Nis, and Tg in thyroid folliculogenesis and regain the same factors in BRAFV600E-driven thyroid tumor development." (PMID 38750011, 2024).
triple-negative breast carcinoma (1 paper, 2023). An invasive breast carcinoma which is negative for expression of estrogen receptor (ER), progesterone receptor (PR), and human epidermal growth factor receptor 2 (HER2). "Indeed, TBX3 expression is significantly lower in basal-like and triple negative breast cancer (TNBC) than in the other subtypes." (PMID 38081972, 2023).
urothelial carcinoma (1 paper, 2015). A malignant neoplasm derived from the transitional epithelium of the urinary tract (urinary bladder, ureter, urethra, or renal pelvis). "Methylation of TBX2 and TBX3 has been found to be associated with urothelial tumor progression, however their full role in urothelial carcinoma is not yet clear." (PMID 26008846, 2015).
cancer (84 papers, 2006 to 2025). A tumor composed of atypical neoplastic, often pleomorphic cells that invade other tissues. "We found that TBX3 is primarily expressed in malignant cells, where TBX3high tumor cells increase the secretion of TGFβ1, which promotes the infiltration of cancer-associated fibroblasts (CAFs), thereby forming an immunosuppressive microenvironment." (PMID 39897553, 2025). "A direct association reportedly exists between TBX3 expression imbalance and malignant tumor onset and progression." (PMID 38911382, 2024). "Transcriptional re-activation of TBX3 is an indispensable molecular event for cancer initiation and progression, which linked BRAF/MAPK pathway activation and CXCR2 ligands-attracted MDSCs infiltration." (PMID 35332119, 2022). "Here the authors show that the mutation supports cancer progression by reactivating the developmental factor TBX3 and promoting the recruitment of myeloid derived suppressive cells." (PMID 35332119, 2022). "miR-17-92 and miR-106b-25 deficient mice deregulate Tbx3 in distinct biological contexts and miR-17-92 also deregulate Tbx3 in cancer stem cells." (PMID 34068962, 2021). "Pathway analysis indicated that the top predicted functional changes for the TBX3 transfectants include alterations in cellular movement, cellular growth and proliferation, cell death, cell survival, and cancer‐associated processes." (PMID 30697731, 2019). "Previously it was suggested that TBX3 promotes an invasive cancer phenotype and more recently it was also shown that increased expression of TBX3 was associated with a poor prognosis in CRC patients." (PMID 29284484, 2017). "Altered TBX3 expression is implicated in the pathogenesis of breast and other cancers by affecting cell adhesion, proliferation and senescence." (PMID 24675841, 2014). "TBX3 is a protein with essential roles in development and tissue homeostasis, and is implicated in cancer pathogenesis." (PMID 24675841, 2014). "In contrast, in cells that received a cancer causing stimulus, TBX3 and CAPERα physically separate: this activates production of UCA1 RNA and causes senescence." (PMID 24876127, 2014). "Furthermore, TBX2 and TBX3 play distinct but causative oncogenic roles in cancers where they are both expressed, and they repress one another to achieve these functions." (PMID 40717225, 2025). "Interestingly, TBX3 is a T-box transcription factor that has been implicated in a wide range of carcinomas) and in regulation of proliferation." (PMID 28212444, 2017). "The association of TBX3 with several factors that regulate response to estrogen and other nuclear hormones is interesting in the context of postulated roles for TBX3 in tumorigenesis and metastasis of hormone responsive breast, prostate and other cancers." (PMID 24675841, 2014). "Indeed, whereas knocking down TBX3 in transformed fibroblasts resulted in a more aggressive cancer phenotype, ectopic overexpression of Tbx3, or its splice variant Tbx3+2a, was sufficient to inhibit key features of the cancer phenotype in the aggressive HT1080 cell line." (PMID 26900951, 2016). "In this study, we focused on TBX3 in the TME of BLCA via a pan-cancer analysis and then further investigated its key role in BLCA using multi-omics analysis." (PMID 39897553, 2025). "This is important because TBX2 and TBX3 can transcriptionally repress one another in certain contexts, and they have been shown to have distinct oncogenic roles in cancers where they are both expressed." (PMID 39912718, 2025). "Our findings are consistent with previous reports that TBX3 promotes cancer cell survival and proliferation by functioning as an anti‐senescence factor and repressing the levels of p16INK4a, pRb and p21WAF1/CIP1." (PMID 40717225, 2025). "This creates a mutual activation loop among Tbx2, Tbx3, and Tbx5, with the notable exception that Tbx3 represses Tbx2, as was reported for cancer cells." (PMID 41278973, 2025).
cancer (continued). "Prior studies have revealed that TBX3 plays a crucial role in carcinogenesis and exhibits abnormal expression patterns in various cancers." (PMID 39897553, 2025). "After that, we focused on the associations between TBX3 and the TME immune status across multiple cancers." (PMID 39897553, 2025). "The levels of TBX3 transcription are often lower intumor tissues than in normal samples, including those fromprostate cancer." (PMID 41164275, 2025). "In this study, for the first time, we focused on TBX3 in the TME of BLCA through pan-cancer analysis and revealed its key role in BLCA using multi-omics analysis and in vitro and in vivo experiments." (PMID 39897553, 2025). "This pan-cancer analysis indicated that TBX3 is primarily expressed in malignant tumor cells, epithelial cells, and fibroblasts across cancers." (PMID 39897553, 2025). "Further, TBX3 has been shown to lead to uncontrolled cell proliferation and evasion of senescence and apoptosis, thereby promoting cancer initiation, angiogenesis, and metastasis." (PMID 39897553, 2025). "This is important, as, if TBX3 proved to be dispensable for homeostasis as BCL9/9L but required for cancer cell survival as TBX5 or β-catenin, its targeting will constitute the proverbial therapeutic window." (PMID 40343989, 2025). "It is worth noting that TBX3 plays an irreplaceable role in the occurrence and development of cancer." (PMID 39897553, 2025). "KEGG pathway enrichment analysis of the TBX3/β-catenin regulated genes showed high-fold enrichment for cancer-related processes." (PMID 40343989, 2025). "Based on bulk RNA-seq data, we found that TBX3 was expressed significantly higher in cancer tissues as compared to normal tissues in both the Xiangya cohort 34,38 and TCGA-BLCA cohort." (PMID 39897553, 2025). "TBX3 is overexpressed in multiple cancers, and it has been shown to contribute to several oncogenic processes and has been validated as a therapeutic target." (PMID 40717225, 2025). "Notable was also the expression of TBX3 in the LGR5+ cell compartment, indicating that TBX3 is likely to function in intestinal epithelial stem cells or cancer stem cells originating from this tissue." (PMID 40343989, 2025). "We then analyzed the relative expression levels of TBX3 at the single-cell level across 33 types of cancer." (PMID 39897553, 2025). "Here, genome-wide binding and transcriptomics analyses reveal that TBX3 regulates cancer metastasis genes in cooperation with Wnt/β-catenin." (PMID 40343989, 2025). "TBX3 has been reported to be abnormally expressed in various carcinomas, including breast, bladder, liver, and pancreatic carcinomas 25-28." (PMID 39897553, 2025). "60.55% of BLCA tissues showed moderate or high expression of TBX3, while this rate only reached to 9.56% in para-carcinoma tissue (p < 0.0001)." (PMID 39897553, 2025). "This is important because it will shed light on versatile ways of targeting TBX2 and TBX3 in cancer therapies." (PMID 39403898, 2024). "Recent studies revealed TBX3 overexpression in diverse cancer types, which facilitates tumor development and progression." (PMID 38909034, 2024). "According to DepMap, the Chronos scores revealed that TBX3 plays an essential function in various malignant tumors, including OS." (PMID 38911382, 2024). "For example, TBX3 is important for stem cell self-renewal and has been found to play an important role in cancer stemness." (PMID 38965548, 2024). "There are significant differences between cancer and sarcoma regarding cell origin and characteristics, resulting in the opposite effects of TBX3." (PMID 38965548, 2024). "CTNNB1 (encoding β-catenin) mutation induces TBX3 expression, which in turn inhibits phospholipase D1 (PLD1) and YAP/TAZ pathway activation, suppressing cancer proliferation and growth." (PMID 38965548, 2024).
cancer (continued). "In these studies, the overexpression always predicted metastasis and poor prognosis in patients, which suggested a promoting effect of TBX3 on malignancy progression in cancer." (PMID 38413457, 2024). "These contrasting data suggest that TBX3 possesses significant functional plasticity across cancers as a tumor suppressor or promoter." (PMID 38909034, 2024). "Aberrant expression of TBX3 has been extensively reported in various human cancers, primarily due to transcriptional dysregulation." (PMID 38750011, 2024). "Niclosamide, piroctone olamine, and pyrvinium pamoate have been shown to exhibit anti‐cancer activity through their ability to inhibit signalling pathways such as the WNT/B‐catenin that can transcriptionally activate TBX2/TBX3." (PMID 39403898, 2024). "Niclosamide, piroctone olamine, and pyrvinium pamoate are promising, cost‐effective therapeutic agents for the treatment of TBX2/TBX3‐dependent cancers." (PMID 39403898, 2024). "TBX3 is a transcription factor frequently overexpressed in various types of human cancers, including BC, while the MAP3K1 gene induces MAP-kinase pathway." (PMID 35637532, 2022). "Nevertheless, TBX3 is frequently overexpressed in several cancers, such as colon cancer, hepatocarcinoma, melanoma, chondrosarcoma, and BC." (PMID 35637532, 2022). "It is therefore of importance to assess downstream transcriptional targets of both TBX3 isoforms in order to thoroughly understand transcriptional changes mediated by each isoform in disease states, including cancer." (PMID 31570773, 2020). "The overexpression of TBX3 is a key feature of several cancers, where it promotes several oncogenic processes, but little is known about its expression status and function in RMS." (PMID 32098189, 2020). "To determine the significance of TBX3 expression in ERMS, cell culture models were established in which TBX3 was either stably overexpressed or knocked down in RD cells, and we measured the impact of altering TBX3 levels on several hallmarks of cancer." (PMID 32098189, 2020). "More recently, it was recognized that although TBX3 promotes migration and invasiveness of cancer cells, it negatively regulates cell proliferation." (PMID 30630509, 2019). "Accumulating evidence suggests that TBX3‐mediated transcriptional repression of p14ARF11, 17 and/or p21CIP116, 18 plays a role in driving cancer progression through bypassing cellular senescence." (PMID 30697731, 2019). "As T‐box proteins such as TBX3 have been shown to have detrimental effects with respect to cancer progression and survival 47, a thorough understanding of the underlying mechanisms involved is crucial." (PMID 30697731, 2019). "As Tbx3 is involved in the carcinogenesis of multiple types of human cancers, our findings suggest an important target for anti-cancer drug development." (PMID 30151243, 2018). "TBX3 transcriptional repression controls expression of cell proliferation and senescence factors; abnormal TBX3 expression occurs in multiple cancers." (PMID 27046536, 2016). "TBX3 is essential in development and has emerged as an important player in the genesis of several cancers where it directly contributes to proliferation, tumour formation, migration and invasion." (PMID 27110270, 2016). "On the other hand, the overexpression of TBX3 is a feature of a wide range of cancers and it is a key driver of several oncogenic processes including proliferation, migration and invasion." (PMID 27110270, 2016). "Of relevance to this study is the evidence suggesting that during embryonic development and cancer, TBX3 impacts on cell proliferation by repressing key cell cycle regulators." (PMID 27110270, 2016). "In summary, results from this study contribute significantly to an understanding of the role of TBX3 in cancer biology and provide new evidence that TBX3 also impacts on sarcomagenesis." (PMID 26900951, 2016).
cancer (continued). "TBX3 is overexpressed in several cancers and has been shown to contribute directly to tumour formation, migration and invasion." (PMID 27110270, 2016). "The transcription factor TBX3, a critical developmental regulator, is overexpressed in several cancers of epithelial origin where it contributes to tumorigenesis by different molecular mechanisms." (PMID 26900951, 2016). "We noted that, over the entire set of somatic cancer genome projects, two types of mutations affecting the ORF were significantly enriched in TBX3 compared to the other TBX genes: frameshift mutations and in-frame deletions." (PMID 26579496, 2015). "Mining the pathways regulated by UCA1 and CAPERα/TBX3 will reveal factors that control cell proliferation and fate during development and disease and thus constitute novel cancer therapeutic targets." (PMID 24876127, 2014). "Further studies will be required to establish exactly how the CAPERα/TBX3 protein complex interacts with DNA and RNA to control senescence and prevent cancer." (PMID 24876127, 2014). "Given the importance of TBX3 in development, human disease, and its potential as therapeutic target for cancer and tissue regeneration, it is essential to define the pathways in which it functions." (PMID 24675841, 2014). "The data presented here are not directly in agreement with the previously published data showing FGF/Tbx3 signalling is responsible for this paracrine signalling in cancers." (PMID 23497505, 2013). "The T-box transcription factor, TBX3, is overexpressed in several cancers and has been proposed as a chemotherapeutic target." (PMID 24098938, 2013). "Previously several mechanisms have been identified which Tbx3 uses during cancer formation and progression." (PMID 23082988, 2012). "Tbx2 and Tbx3, both of which are transcriptional repressors, have been found to be amplified or over-expressed in various cancer types." (PMID 23082988, 2012). "Research towards identifying the molecular mechanisms of Tbx3 in cancer formation revealed that Tbx3 interacts with proteins of several oncogenic pathways." (PMID 23082988, 2012). "The mRNA expression of Tbx3 was found to be significantly increased in cancer samples (min-max: 22–7100, median: 242) with respect to the normal tissue (min-max: 12–1460, median: 5.38) obtained from the same individuals (p<0.001)." (PMID 23082988, 2012). "Both kind of tissues (cancer and normal) were examined pathologically and then analyzed for expression of Tbx3 mRNA and protein levels." (PMID 23082988, 2012). "Previous studies have suggested that TBX3 contributes to cancer development by its ability to bypass senescence by repressing the expression of p14ARF-tumor suppressor." (PMID 22039763, 2011). "A recent study has proposed a model in which the expression of TBX3 in cancer cells promotes the expansion of cancer stem-like cells through paracrine fibroblast growth factor (FGF) signaling." (PMID 22039763, 2011). "As a member of the T-box family, TBX3 plays significant roles in cancer development." (PMID 39897553, 2025). "Moreover, TBX3 reduced the cancer-killing efficiency of CD8+ T cells by decreasing the proportion of GZMB+ CD8+ T cells, and knocking down TBX3 combined with anti-PD-1 treatment increased CD8+ T cell infiltration and reduced CAFs in vivo." (PMID 39897553, 2025). "Interestingly, TBX3 has been shown to promote cancer cell migration via activation of inhibitor of DNA binding 1 (ID1), a negative regulator of CDH1." (PMID 40001874, 2025). "Gene expression analysis of patient-derived human cancer cell lines obtained from the FANTOM 5 Consortium showed that TBX3 is indeed expressed in several tumor types of endo- and mesodermal origin, including, prominently, tumors from the gastrointestinal tract and the liver." (PMID 40343989, 2025).